CPSF4L (cleavage and polyadenylation specific factor 4 like)
Tractability: No criterion of Open Targets' tractability assessment is met for any kind of drug.
Gene: Protein-coding gene on chromosome 17 (73,248,449 to 73,262,352, reverse strand). Ensembl gene ENSG00000187959.
Gene Ontology:
Molecular function: metal ion binding; RNA binding
Cellular component: mRNA cleavage and polyadenylation specificity factor complex
Genetic constraint (gnomAD): Loss-of-function variants: 15 observed, 15.89 expected, observed/expected ratio (o/e) 0.94, 90% interval 0.63 to 1.45. The upper end of that interval is the gene's LOEUF score, 1.45, which puts it in group 6 of 6, group 1 being the genes least tolerant of losing a copy. Missense variants: 185 observed, 200.33 expected, observed/expected ratio (o/e) 0.92, 90% interval 0.82 to 1.04. Synonymous variants: 64 observed, 73.79 expected, observed/expected ratio (o/e) 0.87, 90% interval 0.71 to 1.07.
Homologues: Orthologues: chimpanzee CPSF4L (100% identical), macaque CPSF4L (96% identical), rabbit CPSF4L (77% identical), rat Cpsf4l (72% identical), mouse Cpsf4l (71% identical), Caenorhabditis elegans cpsf-4 (50% identical). Paralogues in human: CPSF4 (63% identical), ZC3H3 (34% identical).
Diseases named in the same sentence as CPSF4L in open-access papers:
CPSF4L is named in the same sentence as 2 diseases in open-access papers, as found by Europe PMC text mining. Sharing a sentence is not in itself a finding about the gene and the disease. The quoted sentences say what the papers report.
acne vulgaris (1 paper, 2024). "After conducting biological annotation, we identified six genes (PLA2G4A, FADS2, TIMP17, ADAMTS9, ZC3H3, and CPSF4L) that may be associated with the pathogenic gut microbiota of acne vulgaris patients." (PMID 38371936, 2024). "The biological annotation analysis indicates that we have identified 3 pairs of associated genes between gut microbiota and acne vulgaris, including PLA2G4A/FADS2, TIMP3/ADAMTS9 and ZC3H3/CPSF4L." (PMID 38371936, 2024).
Obesity (1 paper, 2024). Accumulation of substantial excess body fat. "Some studies have found that ZC3H3 is involved in mediating nuclear RNA decay, and CPSF4L may be associated with obesity." (PMID 38371936, 2024).